IGFBP3 (insulin like growth factor binding protein 3)
Diseases named in the same sentence as IGFBP3 in open-access papers (continued):
Sharing a sentence is not in itself a finding about the gene and the disease.
tumor (continued). "IGFBP3 functions as a mediator of growth suppression signals and a tumor suppressor via the IGF signal pathway." (PMID 38891936, 2024). "While both regulate IGF activity, IGFBP-3 predominantly acts as a tumor suppressor by inhibiting IGF-1 and IGF-2 from activating IGF-1R, thus reducing cell proliferation and promoting apoptosis." (PMID 39585162, 2024). "Having validated IGFBP3 and IGBFP5 as markers of RCC-associated TECs and NECs, respectively, we examined the expression profiles of these genes in tumor and normal tissues in The Cancer Genome Atlas (TCGA) dataset." (PMID 39516665, 2024). "Of the 24 tissue sections, proteins encoded by COL4A1, IGFBP3, and TIMP1 were slightly up-regulated in tumor tissues, while GHRL and GJA1 proteins were relatively down-regulated in tumor tissues than para-tumor tissues." (PMID 38273348, 2024). "Blood glucose and serum insulin, IGF-1 and IGFBP3 were measured at study end when tumor volumes reached 800 mm3." (PMID 38082056, 2024). "The results showed that the viability of Jurkat cells was impaired by co-culture with overexpressing IGFBP3 tumor cells, which was blocked by IGFBP3 antibody and PD-L1 inhibitor." (PMID 38326861, 2024). "In contrast, IGFBP-3 is often downregulated in cancer, leading to reduced tumor-suppressive effects." (PMID 39585162, 2024). "Many tumor suppressors and oncogenes modulated by H2A.J play important roles in the regulation of energy metabolism (IGFBP3; IGFBP4; IGFBP5; AKR1B1; SOD2)." (PMID 39062630, 2024). "In summary, our findings show that knockdown of IGFBP3 attenuates in brain orthotopic tumor formation, and prolongs the survival of mice." (PMID 38326861, 2024). "In tumor cells, we observed activation of genes associated with cell proliferation (TMSB10, IGFBP3), migration (CCL2), signal transduction (DUSP1), and other behaviors." (PMID 38191424, 2024). "Two drugs targeting IGFBP3 were approved for neoplasm treatment and selective COX-2 inhibition, respectively." (PMID 39526184, 2024). "It has been shown that in NSCLC, IGFBP3 mediates growth inhibition and induction of apoptosis to exert a tumor suppressive effect (Hochscheid, Jaques & Wegmann, 2000)." (PMID 37397026, 2023). "In tumor progression, IGFBP3 can either promote or inhibit tumor growth, but the specific mechanism is not fully understood yet." (PMID 37624511, 2023). "According to ROC analysis, IGFBP3 was extremely effective in discriminating early tumor pathologies (stage I and stage II) from normal." (PMID 37397026, 2023). "IGFBP3 was found to be the most upregulated gene in tumor tissues (FC gene chip = 8.15, p = 5.88 × 10−32)." (PMID 36901940, 2023). "Insulin-like growth factor binding protein-3 (IGFBP-3) has been known to inhibit cell proliferation and exert tumor-suppressing effects depending on the cell type." (PMID 37253773, 2023). "Recent studies have also found that IGFBP3 is abnormally elevated in human tongue squamous cell carcinoma (TSCC) and is associated with tumor cell migration and cell growth." (PMID 37397026, 2023). "In this study, we aimed to determine the circulating levels of IGF-1, IGFBP-2, and IGFBP-3 in patients with CRC and to investigate their association with different clinical aspects of CRC, including risk, tumor grade, and tumor stage." (PMID 38137390, 2023).
tumor (continued). "IGFBP3 can affect tumor cell proliferation, apoptosis, DNA damage repair and other processes through IGF-dependent or IGF-independent pathways." (PMID 38062230, 2023). "We also found significantly upregulated myCAF markers in gal 4–KD tumor CAFs, including Col12a1, Col8a1, Thbs2, and Igfbp3." (PMID 36478037, 2023). "This indicates that IGFBP-3 works in a tumor-suppression mode; therefore, it would be logical for it to be downregulated in cancer." (PMID 38137390, 2023). "Taken together, these results lead to the conclusion that IGFBP-3 exhibits tumor suppressor activity; therefore, it would be logical for IGFBP-3 to be reduced in patients with cancer." (PMID 38137390, 2023). "The results revealed that low expression of IGFBP3 was closely correlated with advanced tumor stage (P = 0.020), involvement of >1 extranodal sites (P = 0.033), higher IPI score (P = 0.007), and elevated LDH levels (P = 0.011)." (PMID 36660244, 2023). "Then, in brief, select “Liver Cancer” from the drop-down menu of “Tumor Types”, “IGFBP3” from the drop-down menu of “Gene” on the page, click “Submit” for analysis, and then click “Export Data” to obtain protein expression profile data." (PMID 37397026, 2023). "IGFBP-3 promotes tumor cell migration, at least partially, by modulating the ERK activity in SAS-Fucci cells, regardless of cell-cycle phase." (PMID 35798794, 2022). "A multi-parametric prognostic nomogram, which was composed of serum IGFBP3, tumor size and TNM stage, showed improved performance in individualized prognosis estimation compared with the traditional TNM staging." (PMID 36409444, 2022). "For example, as a result of a higher affinity for IGFs than IGF receptors (IGFRs), IGFBP3 can restrict access of IGFs to IGFRs and consequently inhibit their tumor-promoting effects." (PMID 35945453, 2022). "Conversely, overexpression of SALIS significantly promoted tumor growth and formed bigger xenograft tumors and decreased IGFBP3 and Caspase-7 expression together with the reduction of BAX and generation of cleaved Caspase-3 and Caspase-7." (PMID 35871161, 2022). "Circ-0000285 silencing decreased the oncogenic phenotype in vitro and inhibited xenograft tumor growth in mice, with a concomitant reduction in tumor IGFBP-3." (PMID 35597813, 2022). "IGFBP3 also possesses IGF-independent roles to influence tumor development by modulating cell apoptosis." (PMID 35871161, 2022). "Although studies have suggested a tumor-suppressive role for IGFBP-3, ample evidence in various cancers indicates that its high levels were associated with disease aggressiveness." (PMID 36153549, 2022). "In the endothelial cell (EC) compartment, we identified IGFBP3+ EC and collagen EC subsets showing considerable enrichments in tumor tissues." (PMID 36423636, 2022). "Insulin-like growth factor binding protein-3 (IGFBP-3) is produced by a tumor suppressor gene and inhibits the binding of IGF-1 to IGF-1R, stopping them from encouraging cell proliferation and survival." (PMID 35887304, 2022). "In mice with mammary tumors deficient in IGFBP-3, the intratumoral gene expression levels of Ifn-γ, Cd8, and Tnf-α were elevated, indicating a higher infiltration of CD8+ cytotoxic T cells into the tumor." (PMID 36010994, 2022). "The univariate analysis indicated that tumor size, tumor invasion depth, regional lymph nodes, TNM stage and serum IGFBP3 were associated with OS of EJA patients (P < 0.05)." (PMID 36409444, 2022). "Expression of IGFBP-3 inhibited tumor migration, while suppression of IGFBP-3 with siRNA resulted in resumption of migration activity, suggesting IGFBP-3 has a role in the regulation of cell migration." (PMID 36230617, 2022). "In a study where IGFBP-3 appeared to act as a tumor suppressor, miR-21, which is oncogenic and highly expressed in GBM tissue, was shown to downregulate IGFBP-3." (PMID 35597813, 2022).
tumor (continued). "The following variables remained independently prognostic: serum IGFBP3 (P = 0.005, HR = 0.468; 95% CI 0.275–0.794), tumor size (P = 0.018, HR = 1.993; 95% CI 1.126–3.526) and TNM stage (P = 0.014, HR = 2.010; 95% CI 1.151–3.510)." (PMID 36409444, 2022). "IGFBP3 can enhance mitochondrial-dependent apoptosis of tumor tissues by increasing ROS production through NF-κB activation and cytokine production." (PMID 35154570, 2022). "At the cellular level IGFBP-3 can act either as an oncogene or a tumor suppressor in different cancers." (PMID 35597813, 2022). "Then, we developed and validated a new prognostic nomogram containing serum IGFBP3, tumor size and TNM stage for OS prediction of EJA patients." (PMID 36409444, 2022). "Our nomogram based on serum IGFBP3, tumor size and TNM stage improved the prognostic prediction of EJA with concordance index of 0.735." (PMID 36409444, 2022). "Alternatively, various factors enriched in EVs of hypoxic cancer cells have been shown to limit the infiltration of immune cells into the tumor, including IGFBP-3, TSP-1, and a disintegrin and metalloprotease with thrombospondin motif 1 (ADAMTS1)." (PMID 36010994, 2022). "Although IGFBP-3 can act as a tumor suppressor, its expression in breast cancer is highest in basal-like TNBC and correlates with shorter recurrence-free patient survival." (PMID 35597813, 2022). "Compared with TNM stage, a nomogram based on serum IGFBP3, tumor size and TNM stage indicated an improved C-index in prognostic prediction (0.625 vs. 0.735, P = 0.001)." (PMID 36409444, 2022). "Several studies have also demonstrated that IGFBP-3 knockdown inhibits DNA synthesis and tumor growth." (PMID 35798794, 2022). "In this study, genes including THBS1, CDKN1A, FBN1, TGFB1, and IGFBP3 were found to be downregulated in tumor cell lines." (PMID 35340229, 2022). "Based on these results, combined with those of the mRNA expression analysis, IGFBP3/5/7 were chosen for further study of the mechanisms of tumor progression." (PMID 34745945, 2021). "Breeding P4-pBIG2i-hIGFBP3 or control P4-pBIG2i transfectants on SCID mice, tumor growth was found to be attenuated after IGFBP3 expression." (PMID 34824343, 2021). "To further understand the possible molecular mechanisms of IGFBP3/5/7 in tumor progression, we selected the top 10 genes positively and negatively co-expressed with IGFBP3/5/7 based on TCGA data and constructed a heatmap." (PMID 34745945, 2021). "Our results show that ectopic expression of IGFBP3 decreases tumor growth upon IR, suggesting a role for IGFBP3 in modulating tumor cell radiosensitivity in vivo." (PMID 33712045, 2021). "Although IGFBP3 can effectively downregulate tumor proliferation and vasculogenesis, its effects are only transient." (PMID 34824343, 2021). "Our in vivo data indicate that ectopic IGFBP3 expression increases tumor cell apoptosis and inhibits tumor cell proliferation at 72 h after exposure to IR." (PMID 33712045, 2021). "Further IHC analysis showed IGFBP3 is also highly expressed in NSCLC tumor tissues and is positively correlated with the expression of XBP1 expression." (PMID 34094948, 2021). "In particular, IGFBP3 significantly downregulated ribosomal dysfunction-enhanced tumor cell survival." (PMID 33972671, 2021). "Here, we demonstrate that IGFBP‐3 inhibits cell growth by stimulating the TβR‐V‐mediated tumor suppressor signaling pathway (TβR‐V/IRS‐1/2/PP2A/p130, p107)." (PMID 34485840, 2021). "In vivo, IGFBP3 reduced tumor growth and increased apoptotic signals of tumor tissues in immunocompromised mice treated with IR." (PMID 33712045, 2021). "Conversely, IGFBP3 has antioxidative activity, suppressing ROS, enhancing epithelial-to-mesenchymal transition and motility, which is necessary for tumor progression." (PMID 33712045, 2021).
tumor (continued). "Immunostaining of tumor sections with an anti-Ki-67 antibody showed reduced Ki-67 staining in IGFBP3-expressing tumor sections (n = 25; 13 ± 0.9323% per field) compared to controls after IR (n = 25; 25.95 ± 0.9992% per field; p < 0.0001)." (PMID 33712045, 2021). "Consistent with this, our study observed that HOXD10 suppressed cell migration and invasion and that the low level of HOXD10 was associated with metastasis in CRC, highlighting the critical role of IGFBP3 in HOXD10-mediated tumor-suppressive effect." (PMID 34790580, 2021). "Inhibition of tumor growth in vivo with adjuvant IGFBP-3-Fc with erlotinib versus erlotinib after treatment cessation supports that the combination reduces cell survival." (PMID 32066763, 2020). "Much attention was given to identify a putative receptor for IGFBP-3 since early studies have demonstrated the anti-tumor function of IGFBP-3 in cancer." (PMID 32443727, 2020). "SLPI also plays an important role in the regulation of cell cycle progression by promoting the expression of cyclin D1 and IGFBP-3 in tumor cells." (PMID 32742768, 2020). "For example, in the quiescent epidermis, MMP-19 is a major IGFBP3 degrading MMP, while matrix metalloproteinase-7 seems to degrade IGFBP3 in tumor tissues, enabling IGF bioavailability." (PMID 32500027, 2020). "Recently, the binding of IGFBP-3 to a variety of growth factors was shown to improve the efficacy of anti-cancer precision therapy, counteract numerous mechanisms of tumor resistance, and combat tumor heterogeneity." (PMID 32911852, 2020). "In a similar context, it is known that the increase in insulin-like growth factor 1 (IGF1) and the decrease in IGF-binding protein 3 (IGFBP3) are correlated with tumor formation and metastasis." (PMID 32197410, 2020). "IGFBP3 has been proven to inhibit cell proliferation in breast, lung, colon, prostate, and bone tumor cells and some cell lines to reduce tumor cell growth." (PMID 32500027, 2020). "Colony formation, proliferation, wound healing, transwell, western blot, and in vivo tumor growth and metastasis assays were performed to assess the roles of circ-0046263, miR-133a-5p, IGFBP3 and their interactions in NPC cells." (PMID 32703944, 2020). "Numerous studies show that miR-21-5p promotes carcinogenesis and tumor progression by targeting genes encoding PDCD4, PTEN, BTG2, FasL, IGFBP3, TGF-β1, FBXO11, and TIMP3." (PMID 33396321, 2020). "These in vitro data indicate that IGFBP-3R is indispensable for anti-tumor functions of IGFBP-3 and IGFBP-3R agonistic mAb in a variety of cancer cells." (PMID 32443727, 2020). "CUL4B epigenetically inhibits many tumor suppressors, including insulin-like growth factor-binding protein 3 (IGFBP3), PTEN, and p16." (PMID 33324542, 2020). "The remainder of this review will focus on the IGFBP-3 receptor TMEM219 in human cancer by mainly providing the evidence to date regarding the IGFBP-3/TMEM219 system as an anti-tumor and anti-metastatic signaling in human cancer." (PMID 32443727, 2020). "Among them, TMEM219 appears to be the most critical IGFBP-3 receptor mediating anti-tumor and anti-metastatic activities of IGFBP-3." (PMID 32443727, 2020). "Knockdown of NEAT1 results in the decreased expression of RBPs including hnRNP A2 and IGFBP3, both of which can inhibit tumor proliferation, migration, and invasion in liver cancer cells." (PMID 32653017, 2020). "The results are conflicting, with some studies correlating high tumour IGFBP-3 levels with worse clinical outcome, and others reporting the opposite." (PMID 33352865, 2020). "In our in vitro experiments we found that IGFBP-3 can also undergo a functional switch from being a tumour suppressor to a tumour promoter according to GRP78 status." (PMID 33352865, 2020). "Over the past two decades, a wealth of evidence has revealed both tumor suppressing and tumor promoting effects of IGF/IGF-IR-independent actions of IGFBP-3 depending upon cell types, post-translational modifications, and assay methods." (PMID 32443727, 2020).
tumor (continued). "While all genes were hypermethylated in tumor tissues compared with normal adjacent mucosa, only IGFBP3 methylation shortened disease free survival in CRC patients." (PMID 31390840, 2019). "Kaplan–Meier survival analysis showed that a high tumor IGFBP-3 IHC score (>median), like a high Ki67 score, was significantly associated with shorter survival time, whereas a high apoptosis score was associated with prolonged survival." (PMID 29623068, 2018). "Considering the greater migratory capacity of tumor PaSCs when compared to normal PaSCs, the reduction in IGFBP-3 levels seems to overweigh the elevation of IGFBP-2, resulting in a net increase in the IGF-1 availability." (PMID 29475434, 2018). "We also examined the relationship between nuclear IGFBP-3 and indicators of tumor proliferation and apoptosis." (PMID 29623068, 2018). "Treatment of IGFII up-regulates Igfbp3 expression in KrasG12D/+; p53f/f; Ng2/Cspg4+/+ tumor cells, but this stimulatory effect is lost in the KrasG12D/+; p53f/f; Ng2/Cspg4f/f tumor cells." (PMID 29196603, 2018). "For both cell types, nuclear IGFBP-3 IHC staining in tumor sections was greatly decreased in combination-treated mice compared to controls." (PMID 29623068, 2018). "IGFBP3 also has been shown to facilitate GBM tumor cell proliferation, invasion, and migration through the regulation of STAT-1 signaling." (PMID 30231881, 2018). "Collectively, these results were in line with the prominent role of IGFBP3 as a tumor suppressor, and also revealed broad regulatory effects of PHF5A on cellular functions through multiple signaling pathways." (PMID 29566713, 2018). "The tumour suppressive TAp63 isoforms negatively control Igf1r transcription, whereas Igfbp3 is a target of transcriptional repression by ΔNp63." (PMID 30594912, 2018). "Nuclear IGFBP-3 was inversely correlated with CCasp-3 staining for both tumor types, and survival analysis showed that CCasp-3 staining above the median level was significantly associated with improved mouse survival." (PMID 29623068, 2018). "Low levels of IGFBP3 expression in HCCs were correlated with tumor size, tumor multiplicity, node, metastasis, clinical stage and shorter survival time." (PMID 29702590, 2018). "Similar to our findings, in utero exposure to sodium arsenite in mice combined with repeated postnatal exposure (post-weaning) to tetradecanoylphorbol acetate (a tumor promoter) resulted in increased IGFBP3 gene expression in the liver 21 weeks post-weaning." (PMID 29947889, 2018). "This reinforces that tumor IGFBP-3 expression is involved in driving EGFR-SphK1-dependent proliferation in TNBC cells, and should be evaluated as a possible biomarker of efficacy of the inhibitory drug combination." (PMID 28778177, 2017). "INSR was substantially down-regulated in the tumor samples (median = 0.58; range = 0.01–471.75; RQ < 1 in 84.2% of cases), as was IGFBP-3 (median = 0.52; range = 0.05–2.96; RQ < 1 in 80.7% of cases)." (PMID 28545426, 2017). "IGFBP-3 is an anti-angiogenic and anti-metastatic protein that is upregulated and localized in the nucleus of PCa tumor cells." (PMID 28503095, 2017). "There was additional evidence to suggest that the suppression of IGF-II can reduce tumor size, and contradictory evidence with regards to the effect of IGFBP-3 suppression on tumor progression." (PMID 28361446, 2017). "When IGF-I levels were reduced by producing antibodies against IGF-I, tumor volume was reduced relative to controls, whereas tumor volume was higher in IGFBP-3 knockout animals." (PMID 28361446, 2017). "In the CRC, the correlation of ADAM28 and CRC tumorigenesis has not yet been established, although transcripts of ADAM28 and IGFBP-3 genes in fresh CRC tumor specimens were primary examined in CRC patients with overweight or obese using a microarray analysis." (PMID 27661126, 2016).